RNU6-485P (RNA, U6 small nuclear 485, pseudogene)
Gene: Small nuclear RNA gene on chromosome 12 (7,118,785 to 7,118,891, forward strand). Ensembl gene ENSG00000200345.
Homologues: Orthologues: chimpanzee U6 (95% identical), macaque U6 (93% identical), dog U6 (73% identical), guinea pig U6 (70% identical). Paralogues in human: RNU6-727P (86% identical), RNU6-1094P (84% identical), RNU6-242P (84% identical), RNU6-338P (84% identical), RNU6-378P (84% identical), RNU6-544P (84% identical), RNU6-1019P (83% identical), RNU6-1056P (83% identical), RNU6-1124P (83% identical), RNU6-12P (83% identical), RNU6-13P (83% identical), RNU6-24P (83% identical), and 1283 more.